IL2RG (interleukin 2 receptor subunit gamma)
Diseases named in the same sentence as IL2RG in open-access papers (continued):
Sharing a sentence is not in itself a finding about the gene and the disease.
cancer (39 papers, 2009 to 2025). A tumor composed of atypical neoplastic, often pleomorphic cells that invade other tissues. "For example, mRNA encoding IL2RG, the gamma subunit common to the IL-2, IL-4, IL-7 and IL-21 receptors, is overexpressed by 155% in platelet-educated cancer cells." (PMID 40096084, 2025). "We uncovered a positive association between IL-2RG expression and the prognosis of cancer patients undergoing various immunotherapy treatments, including those involving anti-PD1, anti-PD-L1, and anti-CTLA-4." (PMID 38720389, 2024). "High expression of CCR7, IL2RG, CXCL9 and MAPK10 was associated with elevated drug sensitivity of cancer cells, while high expression of FLT3 was associated with diminished drug sensitivity of cancer cells to one drug (INK-128)." (PMID 38438469, 2024). "Using The Cancer Genome Atlas dataset, a 5-CD8Gs risk model (KLRB1, FYN, IL2RG, FCER1G, and DGKZ) was constructed, which was verified in International Cancer Genome Consortium and gene expression omnibus datasets." (PMID 38489709, 2024). "Leveraging the insights of the interactive BodyMap and Pancancer view, we discerned pronounced discrepancies in IL-2RG transcriptional expression, most saliently cancers within digestive system organs, encompassing the pancreas, stomach, and colon." (PMID 38720389, 2024). "These collective findings, consistent with our results, reinforce the significance of IL-2RG in cancer biology." (PMID 38720389, 2024). "Although the IL-2RG gene has been relatively understudied in cancer research, emerging evidence highlights its role in tumorigenesis." (PMID 38720389, 2024). "Recent research endeavors have focused on assessing the response to anti-cancer therapy through the perspective of IL-2RG." (PMID 38720389, 2024). "The L-R pair of IL7-(IL7R + IL2RG) was enriched between cancer cells and immune cells in EEC-II group, which plays a crucial role in the survival and differentiation of lymphocytes via IL7 receptor." (PMID 39112478, 2024). "Most recently, we have employed the IL2RG KO hamsters to create patient-derived xenograft (PDX) cancer models, in particular for metastatic pancreatic cancer." (PMID 35954238, 2022). "This IL2RG knockout female pig model will greatly contribute not only to cancer and stem cell research but also to preclinical evaluations of the transplantation of pluripotent stem cells, such as iPS cells." (PMID 27809915, 2016). "Finally, we have also showed the overexpression of genes whose role in cancer is not yet well understood such as IL2RG, CACNA1D and GNRH1." (PMID 40096084, 2025). "These collective results imply that IL-2RG might serve as a promising predictive biomarker for patients’ response to immunotherapy in diverse cancer types." (PMID 38720389, 2024). "Thus, we conducted further investigations to examine the connection between IL-2RG expression and the effectiveness of cancer immunotherapies." (PMID 38720389, 2024). "This novel Il2rg KO Syrian hamster line might also be useful for studying cancer immunology, as well as being used as a host for human stem cell and cancer cell transplantation research." (PMID 32651192, 2020). "Finally, we have identified mRNAs encoding proteins such as IL2RG (155%), GNRH1 (153%) and CACNA1D (130%) that are overexpressed and whose role in cancer remains unclear." (PMID 40096084, 2025). "To begin, the findings regarding the oncogenic and immunological functions of IL-2RG are derived from bioinformatics analyses of multiple online datasets, underscoring the need for further experimental validation to substantiate its involvement in cancer-related processes." (PMID 38720389, 2024). "In specific, TIS is referred to as an 18‐gene signature (CCL5, GZMK, CD3D, CD3E, CD2, HLA‐DRA, IL2RG, NKG7, CIITA, CXCR6, LAG3, TAGAP, HLA‐E, CXCL13, IDO1, CXCL10, STAT1, and GZMB), which was related to the response to ICIs in various cancers." (PMID 37434432, 2023).
cancer (continued). "Generated by knocking out the expressions of Prkdc and IL2rg in NOD mice using the CRISPR genome editing technique, these mice lack T, B, and NK cells and are ideal for engraftment of human cancer cells." (PMID 37279992, 2023). "In this report, we characterized a Rag2, Il2rg double knockout rat model on the Sprague-Dawley strain, the SRGTM rat, and demonstrated that it is a competent host for human cancer cell lines, PDX modeling, and drug efficacy studies in oncology (SRG OncoRat®)." (PMID 33027304, 2020). "However, the ability of IL2RG−/Y pigs to host human cancer cells remains unclear." (PMID 32871045, 2020). "We purified ROR1+ and ROR1- cancer cell population using flow cytometry and orthotopically injected 5000 cells into 7-week old female NOD/SCID/Il2rg−/− (NSG mice, Jackson Laboratories, 005557)." (PMID 31137681, 2019). "Il2rg expression was not upregulated in any of these three tumors but there is precedent for cancer genes being dysregulated without gross overexpression or at specific developmental stages." (PMID 19461887, 2009). "Furthermore, the relationship between GSDME and IL2RG across various cancers was corroborated by the TIMER2 database, hinting at a potential indirect mechanism in which IL2RG activation may enhance GSDME-mediated pyroptosis." (PMID 40830889, 2025).
infection (30 papers, 2014 to 2026). The state of being infected such as from the introduction of a foreign agent such as serum, vaccine, antigenic substance or organism. "The child was diagnosed with severe combined immunodeficiency disease (IL2RG gene mutation) and was given meropenem, fosfomycin, voriconazole, caspofungin, teicoplanin, and sulfofen for anti-infection." (PMID 34627155, 2021). "We therefore recovered full-term IL2RG knockout piglets recovered via cesarean section (114 d of gestation) to avoid any risk of infection during parturition." (PMID 27809915, 2016). "One RAG2/IL2RG deficient Gn pig was euthanized at 3 days of age due to general weakness rather than illness caused by pathogens; and one was used as a mock infection control." (PMID 27118081, 2016). "To ask the question of whether these key cellular aspects of the innate (NK) and adaptive (B and T cells) impact SARS-CoV-2 replication and associated disease, we assessed infection in IL2RG KO hamsters." (PMID 33251966, 2020). "Consequently, piglets carrying homozygous RAG1, RAG2, or IL2RG mutations (A632-2, A632-1), which looked normal and strong upon birth, died 12 and 49 days after birth, respectively, due to infection in the lung." (PMID 31253764, 2019). "The dams were sacrificed on 3–9 days post-infection (dpi) to prevent a reduced health status normally occurring in Rag2-/-Il2rg-/- and Ifnar1-/- pregnant mice upon infection with high MCMV doses." (PMID 41288331, 2025). "In patient P3, an 8.5-month-old male infant with persistent, progressively worsening infection of the lower respiratory tract and a Τ−Β+ΝΚ− SCID phenotype, we identified the c.437T>C (p.Leu146Pro) variant in the IL2RG gene." (PMID 41011036, 2025). "hCsf2/Il3 DKI mice exhibited ~103-fold increased lung CFUs 24 h after SPn14 infection alone, as compared with Rag2-/-Il2rg-/- controls." (PMID 37771584, 2023). "To study the effects of the Il2rg inactivation in our hamster strain, we chose to assess how knockout animals responded to infection with human adenovirus." (PMID 32651192, 2020). "Il2rg KO hamsters raised a subpar immune response to HAdV-C6 infection, with major defects in both the humoral and cellular arms of the immune system." (PMID 32651192, 2020). "The maternal uncle of the IL2RG-SCID patient had died of an infection in early childhood, and the maternal grandmother was a carrier of the IL2RG variant." (PMID 32754152, 2020). "The HCMV UL83/pp65-derived NLV-peptide was presented by transgenic HLA-A2.1 in the context of a lethal infection of NOD/SCID/IL-2rg-/- mice with a chimeric murine CMV, mCMV-NLV." (PMID 26181057, 2015). "The other 3 IL2rg/RAG1 KO rabbits died within 2 months (because of infection) when kept in cleaner conditions in isolation after weaning." (PMID 25408890, 2014). "Furthermore, BALB/c Rag2-/-Il2rg-/- mice were competent in acute bacterial clearance before and after PR8 or X31 infection, despite their deficiency in adaptive antiviral immunity." (PMID 37771584, 2023). "Interestingly, elimination of host adaptive immune responses in the IL2RG KO model resulted in a chronic infection persisting at least 24 days." (PMID 33251966, 2020). "Similar to immunocompetent Syrian hamsters, following infection with 5 × 104 ID50 (high dose; 105 TCID50) of SARS-CoV-2, four (2 males, 2 females) IL2RG KO hamsters lost approximately 5-10% of their body weight over the first 5 days following infection before recovering." (PMID 33251966, 2020). "Finally, we tested the capacity of Mtb-infected pHSCs of human LTBI and of mice 28 days p.i. to resuscitate active infection upon intratracheal application into the trachea of Rag2–/–Il2rg–/–mice." (PMID 28046053, 2017). "IFN-γ levels at the site of infection were increased by IL-33 treatment in ILC-sufficient Rag1−/− animals, but were unaffected in Rag2−/−; Il2rg−/− animals." (PMID 33929319, 2021). "Conversely, prior PR8 infection impaired acute bacterial clearance in BALB/c WT but not Rag2-/-Il2rg-/- mice." (PMID 37771584, 2023).
infection (continued). "However, expression of Alox12, Alox12e, Alox8, Alox12b, Il13rα1, Il4rα, Il2rg, and Il13 were not altered following Hpb infection." (PMID 40490052, 2025). "In histological sections of lungs of the Rag2–/–Il2rg–/–mice transplanted with either human pHSCs from LTBI or mouse pHSCs from Mtb-infected mice, we observed increased cellularity in the lungs indicative of an inflammatory infiltrate in response to an active infection 3 weeks after pHSC transfer." (PMID 28046053, 2017). "Interestingly, Il2rg and Itgb2 stand out as two robust reference genes for gene expression analysis in spleens of BALB/c mice, regardless of infection with an intracellular parasite whose target organ is spleen, among others." (PMID 27668434, 2016).
bacterial infection (2 papers, 2020 to 2024). "As previously reported, because KO mice show defects in the development of NK cells, we adoptively transferred WT and KO NK cells into Rag2−/− × Il2rg−/− mice to evaluate the impact of NK cells during bacterial infection." (PMID 33327533, 2020).
infectious disease (2 papers, 2020 to 2022). A disorder directly resulting from the presence and activity of a microbial, viral, or parasitic agent in humans. "All things considered, Il2rg KO Syrian hamsters provide a new tool for studying the immunological disorders caused by IL2RG deficiency in humans and the associated infectious diseases in this important model animal." (PMID 32651192, 2020). "The use of these IL2RG KO hamsters as an XSCID model to study the infectious diseases that are of great health concern in immunocompromised patients was reported by us." (PMID 35954238, 2022). "Therefore, we sought to develop a non-murine model to study XSCID and the infectious diseases associated with IL2RG deficiency." (PMID 32651192, 2020).
cardiovascular diseases (1 paper, 2025). "Literature review revealed that SELP and PECAM1 are associated with angiogenesis and cardiovascular diseases, while CXCR4, IL2RG, and CD48 are primarily involved in immune responses." (PMID 40612110, 2025).
IL2RG also shares sentences with these, for which no sentence is quoted: DiGeorge syndrome (5 papers); Bruton agammaglobulinemia (2); common variable immunodeficiency (2); Crohn disease (2); hematologic diseases (2); parasitemia (2); T-cell acute lymphoblastic leukemia (2); tetanus (2); acute liver failure (1); adult T cell leukemia (1); albinism (1); androgenetic alopecia (1); Aristolochic acid nephropathy (1); ataxia telangiectasia (1); atopic dermatitis (1); autoinflammatory syndrome (1); beta thalassemia (1); bone marrow failure (1); bone metastasis (1); brain cancer (1); bronchiectasis (1); cardiomyopathy (1); cartilage-hair hypoplasia (1); Chronic colitis (1); chronic granulomatous disease (1); chronic lymphocytic leukemia (1); chronic obstructive pulmonary disease (1); colon adenocarcinoma (1); complement deficiencies (1); dengue (1).
A further 74 diseases each share a sentence with IL2RG in 1 paper.